LEP (leptin)
Diseases named in the same sentence as LEP in open-access papers (continued):
Sharing a sentence is not in itself a finding about the gene and the disease.
Obesity (continued). "Differences between studies may be attributed to the bias due to the inclusion of women with obesity, as it appears that obesity impairs the function of leptin in breast milk by mechanisms that are under investigation." (PMID 34523036, 2022). "Both LEP 2548AA and LEPR Q223R were positively correlated with obesity risk." (PMID 36551995, 2022). "The hypothesis behind obesity-induced hypertension involves the downstream effects of hypothalamic leptin signaling and the activation of specific melanocortin receptors located on sympathetic neurons in the spinal cord." (PMID 36293177, 2022). "Leptin, regulates adipose mass and body weight by inhibiting food intake and stimulating energy expenditure, whereas adiponectin plays a vital role in improving obesity and metabolic diseases, and it is induced during adipocyte differentiation." (PMID 35369595, 2022). "Chronic administration of JTT-551 to mice with diet-induced obesity showed anti-obesity effects, improved resistance to leptin and lipid disorders, and may also mediate glucose metabolism abnormalities." (PMID 35806030, 2022). "It was not surprising that a lower adiponectin/leptin serum ratio was also directly associated with obesity and airway inflammation exacerbation in patients with COPD." (PMID 35806353, 2022). "Thus, the primary endpoint was the answer to the question how many children with short stature and obesity had elevated TSH levels co-occuring with elevated leptin levels." (PMID 35399935, 2022). "However, the failure of high leptin levels to correct the metabolic imbalance seen in obesity has given rise to the concept of “leptin resistance”, in which tissues have decreased sensitivity to leptin." (PMID 35054972, 2022). "Lower leptin secretion in mouse adipocytes 3T3-L1 after incubation with LPS mimicked inflammation in obesity, i.e., consuming antioxidant additives might lead to lower leptin secretion and contribute to the obesogenic environment." (PMID 35625608, 2022). "Some studies illustrated that leptin, one of the adipokines related to obesity, could increase the production of proteases and nitric oxide so as to cause low back pain." (PMID 36082069, 2022). "Such decreased leptin sensitivity is most often seen in adults with obesity, but it is an open question for future research whether such a hypothetical mechanism may be operational across different BMI- and age groups." (PMID 35656230, 2022). "People with obesity produce more leptin than those of a normal weight." (PMID 35216099, 2022). "Our findings imply that LEP SNPs may affect IVDD due to the mechanical stress of obesity and leptin expression induced by inflammation in adipose tissue." (PMID 36293132, 2022). "The presence of polymorphisms in the leptin, adiponectin, and TNF-α genes in adult individuals may alter serum adipokine concentrations and predispose obesity." (PMID 35703718, 2022). "In fact, the effect of leptin on bone metabolism is related to factors such as weight and obesity." (PMID 35993023, 2022). "Hyper-leptinaemia could explain the high TSH levels seen in obesity, while estradiol stimulation of leptin could represent the biological basis for gender differences of TSH levels in this cohort." (PMID 36313780, 2022). "p62-KO mice show hyperphagia-induced obesity secondary to abnormal leptin signaling." (PMID 36439272, 2022). "Leptin resistance is almost always discussed and defined as a failure of pharmacological doses of peripherally administered leptin to suppress food intake and body weight with the presence of diet-induced obesity." (PMID 36394061, 2022). "Importantly, other factors closely involved in obesity have been described as promoters of many diseases in the last decades, such as the adipokines leptin or adiponectin." (PMID 36555171, 2022). "Thus, leptin is one of the most well-known and widely studied pro-inflammatory adipokines involved in the development of obesity and its complications." (PMID 36499312, 2022).
Obesity (continued). "This dichotomy in leptin signalling throughout obesity dramatically affects ovarian function." (PMID 36855701, 2022). "In summary, the data suggest that a HFD may reduce leptin sensitivity and that obesity may induce inflammatory processes." (PMID 35563589, 2022). "Leptin mediates the inflammatory response to C. difficile toxin A, and the increase of leptin in obesity thus may partially explain the increased severity of CDI." (PMID 35093158, 2022). "TSH-variability in 800 patients with obesity was mainly explained by leptin independently of BMI, suggesting that TSH might be associated with energy balance rather than obesity." (PMID 34992244, 2022). "In addition, pro-inflammatory cytokines increase leptin synthesis and release, which perpetuates the chronic inflammatory state characteristic of obesity." (PMID 35422689, 2022). "Indeed, the PI3K-AKT signaling pathway, a well-known regulator of cancer metabolism, is regulated by several growth factors, such as insulin, IGF-1, and leptin, whose levels are modified in obesity." (PMID 35158830, 2022). "However, while leptin concentrations are elevated in obese patients, the efficacy of the anorexigenic effect of leptin is decreased during obesity (leptin resistance)." (PMID 35208906, 2022). "Furthermore, the long-term HF diet also led to metabolic disorders such as increases in circulating insulin and leptin levels, indicative of insulin and leptin resistance, as classically reported in animal models of diet-induced obesity." (PMID 35498414, 2022). "As will be discussed in more detail, chronic low-grade inflammation, as well as elevated levels of leptin—a frequent observation in obesity—disrupts the immune system in a number of ways, increasing the risk for severe COVID-19, as well as for a severe course of other infectious diseases." (PMID 35406000, 2022). "Since both obesity and lymphomas are prevalent pathophysiological conditions worldwide and their incidences have increased over the last few years, here we review the possible role of leptin as a promising proinflammatory mediator promoting lymphomas." (PMID 36555171, 2022). "A greater chance of obesity was observed in patients who had leptin AA/AG haplotypes (rs7799039) (OR 3.9; 95% CI 1.4–12.1; p=0.003) and adiponectin (rs17300539) (OR 8.4; 95% CI 1.8–72.2; p=0.001) when compared to GG haplotypes, but not significant for patients’ TNF-α haplotypes." (PMID 35703718, 2022). "The main roles of leptin are in energy hemostasis and to function as an anti-obesity hormone." (PMID 36698957, 2022). "Thus, this study investigated the correlations between body composition and leptin and 25(OH)D levels in boys and girls stratified degree of obesity by %BF." (PMID 35721764, 2022). "Obesity increases systemic levels as well as cellular secretion of many cytokines and adipokines including leptin, IL6, TNFα, IGF1, fatty acid binding protein 4 (FABP4), and resistin, which are all involved in regulating the pathways associated with the development of CSCs in breast cancer tissue." (PMID 36010901, 2022). "Generally, it is attractive to propose that perturbed leptin signalling observed during obesity, has detrimental effects as early as the oocyte stage, which further predisposes them to embryo developmental abnormalities and even metabolic diseases in the offspring." (PMID 36855701, 2022). "Taken together, these results indicate that obesity, characterized by excess adipose tissue, leads to elevated leptin production and generates the low-grade inflammation state that characterizes obesity, and then promoting metabolic disorders and autoimmune inflammatory diseases." (PMID 35270000, 2022). "Leptin is known as the obesity hormone and is mainly produced by adipocytes." (PMID 35745214, 2022).
Obesity (continued). "Obesity results in inflammation, oxidative stress; abnormal lipid metabolism; the activation of the renin angiotensin–aldosterone system; and insulin resistance by producing adiponectin, leptin, and resistin, leading to renal function deterioration." (PMID 35628912, 2022). "In obesity, there is an increased production of leptin, a polypeptide produced from adipocytes that stimulates sympathetic activity leading to renal water retention, increased heart rate, and peripheral vascular resistance, and finally increased blood pressure beyond the target." (PMID 36243876, 2022). "Lastly, our findings suggest that LRG1, chemerin, leptin, and HsCRP might be part of a common pathway involved in the development of obesity, possibly through P38/MAPK signaling pathway." (PMID 35955698, 2022). "A deficit of leptin can lead to obesity, insulin resistance and glucose tolerance impairment." (PMID 35204231, 2022). "In light of our results and the link between homocysteine and obesity, it is possible that homocysteine plays a key role in leptin resistance by inducing ER stress, contributing to the development of obesity and metabolic syndrome in conditions of hyperhomocysteinemia." (PMID 36512575, 2022). "Moreover, in a cross-sectional study of men with BMIs from normal to severe obesity, circulating leptin was inversely correlated with testicular response to hCG stimulation." (PMID 35834069, 2022). "Further study with adipokines, examining for leptin or insulin resistance, and studies in populations with greater prevalence of obesity/severe obesity may be informative." (PMID 36319665, 2022). "Similarly, in animal models of high-fat diet-induced obesity, switching to a balanced chow diet restored standard methylation patterns of LEP promoters, SREBF1 (sterol regulatory element-binding transcription factor 1), PGC1A, and FASN." (PMID 35163268, 2022). "Equally true is that most subjects with obesity are not deficient in leptin, rather exhibit higher circulating leptin levels than those in non-obese subjects, which is a feature of leptin resistance." (PMID 34523036, 2022). "This probably indicates the prevalence of leptin resistance behind the pathogenesis of obesity." (PMID 35388304, 2022). "DIO and genetic models of obesity reported increased leptin and resistin levels." (PMID 36135388, 2022). "In addition to the leptin-melanocortin pathway, some genes that normally build up basic cellular function are recently found to contribute to obesity-related phenotypes." (PMID 33826123, 2022). "As described in the literature, serum leptin concentrations are directly proportional to fat mass and are increased in obesity and pregnancy due to maternal weight gain as well as the placenta’s secretion, contributing to the insulin resistance and GDM pathophysiology." (PMID 35329840, 2022). "In addition, the degree and duration of obesity, which determine the amount of exposure to leptin, greatly affect T-cell phenotypic changes." (PMID 36685567, 2022). "In obesity, DPP4 serum concentration was associated with increased macrophage infiltration of vWAT, high serum levels of leptin, and reduced adiponectin levels, as well as increased circulating levels of inflammatory cytokines, particularly IL-6, IL-12, and TNF-α." (PMID 36499312, 2022). "In obesity, increased concentration of leptin occurs, simultaneously with leptin resistance." (PMID 35406070, 2022). "A similar study can be done in the future, using leptin data in women with obesity." (PMID 35480480, 2022). "The obesity panel revealed BDNF was increased while both leptin and glucagon were reduced." (PMID 35574470, 2022). "Thus, it appears that proinflammatory cytokines and leptin form a vicious circle that promotes the development of chronic inflammation and obesity." (PMID 36119080, 2022). "Additionally, several LEP and LEPR polymorphic profiles are associated with obesity, with only a small number of patients with early-onset extreme obesity being reported." (PMID 35563103, 2022).
Obesity (continued). "Furthermore, high salt intake is reported to induce leptin resistance and obesity to increase hepatic fat accumulation in mice, and it tended to be linked to nonalcoholic fatty liver disease risk in human beings in a meta-analysis of observational studies." (PMID 35804768, 2022). "The explanation could be that circulating serotonin interacts with leptin in adipose tissue and increases the feeling of satiety; therefore, it could be considered protective against obesity." (PMID 35581625, 2022). "Earlier work from our laboratory demonstrates that high glucose, mimicking diabetes, and high leptin, mimicking obesity, upregulate the expression of a potent proatherogenic protein, thrombospondin-1 (TSP-1), in human and mouse aortic smooth muscle cells (SMC)." (PMID 36505365, 2022). "However, it is worth noting that the impact of leptin on body composition and energy metabolism are most notable in models of high calorie feeding and obesity, and less so in low calorie or calorie-restricted models." (PMID 35721743, 2022). "Leptin plays a role in the pathogenesis of both diabetes and obesity." (PMID 35831939, 2022). "In addition, obesity and related hormones, such as leptin, play an instrumental role in regulating food intake and contributing to childhood obesity." (PMID 36499740, 2022). "Recently, new treatment strategies for leptin pathways have emerged, showing the potential to modify these rare forms of obesity, where there is no causal therapy available." (PMID 35563103, 2022). "Moreover, KSK-74 significantly compensated for metabolic disturbances that accompany obesity, such as an increase in plasma triglyceride, resistin, and leptin levels; improved glucose tolerance; and protected experimental animals against adipocyte hypertrophy." (PMID 35806019, 2022). "For example, obese patients, especially females, showed increased levels of serum leptin as a risk marker of obesity, indicating that leptin is not utilised efficiently to regulate body weight, a phenomenon called “leptin resistance”." (PMID 36012601, 2022). "We believe that the theory we have introduced via this piece of writing could represent a starting point in the context of leptin-based therapies and not only for obesity." (PMID 36278579, 2022). "However, in obesity, leptin resistance is accompanied by hyperleptinemia; the latter is a feature shared with psoriasis." (PMID 35886846, 2022). "Importantly, β2-tanycytes have been recently suggested to allow the passage of leptin into the cerebrospinal fluid and to be involved in the obesity-induced leptin resistance." (PMID 34360816, 2021). "It has been shown that leptin can cause changes in the ECM, and an increase in its level leads to cardiomyocyte apoptosis and oxidative stress, thereby leading to structural and functional changes in the heart in patients with obesity." (PMID 34088886, 2021). "Therefore, it is important to place in perspective a historical timeline of preclinical models used in research and development to study the effects of leptin in obesity and T2DM." (PMID 34063911, 2021). "Another interesting study showed that leptin and IL-6 induce anorexia by acting on the lateral parabrachial nucleus (lPBN) in the brain, suggesting that targeting leptin might be controlling the IL-6 signaling in individuals with obesity." (PMID 34220807, 2021). "Then the CRP binds to leptin and decreases its physiological functions in the central and peripheral nervous system, which may be involved in leptin resistance and obesity." (PMID 34068679, 2021). "Leptin-induced RAAS activation and entothelin-1 synthesis may contribute to endothelial dysfunction and obesity-associated arterial hypertension." (PMID 34202323, 2021). "Because these changes occurred in response to both high-fat diet and the absence of leptin (ob/ob), this result indicates that these DETFs are associated with obesity, not with leptin deficiency nor with the content of diet." (PMID 33748705, 2021).
Obesity (continued). "In contrast to the central role of leptin in modulating NK cell number and activity in lean individuals, post-receptor signaling components (protein kinase B pT308, Janus kinase-2p) of leptin were differentially abrogated despite the up-regulated leptin and leptin receptors in subjects with obesity." (PMID 34373739, 2021). "However, the additive effect of WPI and ABX on adiposity and leptin production suggest that WPI has a gut microbiota‐independent protective effect against HFD‐induced obesity." (PMID 34057306, 2021). "However, numerous animal and clinical studies showed discrepancies concerning the effects of probiotics on obesity and their impact on serum leptin levels or leptin expression." (PMID 34568404, 2021). "Obesity is associated with an imbalance of endocrine hormone signaling, especially impairments in insulin/IGF-1 pathway, decrease of adiponectin signaling, and leptin over-secretion and resistance." (PMID 33827616, 2021). "Factors that contribute to increased sodium reabsorption in obesity include adipokines, particularly leptin, which may contribute to renin–angiotensin–aldosterone system activation." (PMID 35052684, 2021). "Leptin-activated STAT3 phosphorylation, as proved in the hypothalamus of lean wild-type animal, becomes a marker frequently employed in the assessment of central leptin signaling in the case of leptin resistance, similar to the situation in most obesity of humans and rodents of DIO." (PMID 33849593, 2021). "Mutations in the leptin-melanocortin signaling pathway, most of which occur in the melanocortin 4 receptor (MC4R), may account for much of the heritability of obesity: an estimated 1 in 200 obese people worldwide have disease-causing mutations in MC4R." (PMID 34777390, 2021). "Thus, disruption in ovarian leptin signaling during obesity can well affect steroidogenesis and the maintenance of channels for intercellular communication during preovulatory follicle formation." (PMID 33924072, 2021). "However, considering the role leptin plays in IR, fibrosis, and HCC, carefully monitored controlled studies with appropriate clinically relevant models need to be performed to use leptin inhibitors as a potential therapy for obesity-induced HCC." (PMID 33671547, 2021). "Normal-weight individuals and women also have a higher variation of leptin levels after stress, suggesting that leptin may have implications in obesity development in response to stress in a sex-dependent manner." (PMID 34684349, 2021). "Leptin resistance in hypothalamic neurons plays a key role in exacerbating diet-induced obesity." (PMID 34268308, 2021). "Collectively, the literature suggests that both sarcopenia and obesity may promote a hyperleptinaemic environment that drives peripheral leptin resistance via the downregulation of its receptor." (PMID 33528828, 2021). "Leptin is a known pro-myeloma adipokine factor that is also increased in obesity." (PMID 33498240, 2021). "In addition, significant differences were found in leptin levels in patients with high degrees of obesity." (PMID 33440802, 2021). "This study was done to determine whether a relationship may exist between CIH and obesity, and body energy balance and leptin signaling during CIH." (PMID 35153807, 2021). "The exact reason for the upregulation of leptin during obesity is unknown, but it has been speculated that leptin may be a critical link between obesity and cancer." (PMID 34572888, 2021). "AMGB was found to be related to the adipocytokine signaling pathway, implying that AMGB may be beneficial in preventing obesity via regulating insulin and leptin signaling pathways." (PMID 34944525, 2021). "In contrast to leptin, adiponectin is reduced in obesity and increased in response to fasting." (PMID 34234682, 2021).